SOX4 (SRY-box transcription factor 4)
Diseases named in the same sentence as SOX4 in open-access papers (continued):
Sharing a sentence is not in itself a finding about the gene and the disease.
glioblastoma (32 papers, 2010 to 2025). The most malignant astrocytic tumor (WHO grade IV). "Previously, TGF-β signalling activity has been found to be upregulated in perivascular niches and closely associated with stemness markers such as Id1, CD44, Sox4 and Sox2, suggesting an underlying inherent plasticity of glioblastoma tumour cells." (PMID 39724753, 2024). "In fact, high SOX4 expression was found to be associated with better prognosis for glioblastoma patients." (PMID 35721477, 2022). "Recently, aberrant Sox4 expression has been observed in various cancer types, including breast, bladder, glioblastoma, liver and colorectal, and associates with poor prognosis and disease progression 28-31." (PMID 31892841, 2020). "Conversely, Sox4 overexpression in PTEN-deficient U87 glioblastoma cells decreased invasion (P < 0.01, unpaired t-test)." (PMID 30683134, 2019). "In addition, miR-29a robustly promotes invasion in PTEN-deficient glioblastoma cells by repressing translation of the Sox4 transcription factor, and this upregulates the invasion-promoting protein, HIC5." (PMID 30683134, 2019). "Although it alone can induce differentiation of glioma stem‐like cells, NGN2 requires SOX4 or SOX11 for highly efficient neuronal reprogramming of human glioblastoma cells." (PMID 39390804, 2024). "In this study, we examined the molecular mechanism by which SOX4 or SOX11 enables NGN2 to highly efficiently reprogram human glioblastoma cells into neurons." (PMID 39390804, 2024). "In conclusion, our study has empirically demonstrated that NGN2 and SOX4/11 can reprogram glioblastoma cells into neurons with high efficiency." (PMID 39390804, 2024). "SOX4 provides one of the few examples identified to date, as it was found, when overexpressed in glioblastoma cells, to bind 126 tRNA genes and diminish their ability to recruit TFIIIB and hence pol III, resulting in selective repression." (PMID 38339234, 2024). "LINC00470 and EGR2 mRNA expression gradually decreased with increasing concentrations of temozolomide in glioblastoma cells, and SOX4 expression was reduced in cells by temozolomide and LINC00470 knockdown." (PMID 36987665, 2023). "In the overlap analysis, we found the overexpression of ABCA13, PEG3, and SOX4 that have been shown to be poor prognostic markers in other cancers including ovarian, glioblastoma, and colon." (PMID 37370820, 2023). "Conclusively, temozolomide repressed glioblastoma progression by repressing the LINC00470/EGR2/SOX4 axis." (PMID 36987665, 2023). "Specifically, temozolomide treatment restricted cell invasion, migration, and angiogenesis but facilitated cell autophagy and apoptosis in glioblastoma via the inactivation of the LINC00470/EGR2/SOX4 axis." (PMID 36987665, 2023). "Intriguingly, our study identified that SOX4 overexpression also abrogated the therapeutic effect of temozolomide treatment on glioblastoma." (PMID 36987665, 2023). "In this study, LINC00470 knockdown or temozolomide treatment both diminished SOX4 expression in glioblastoma cells." (PMID 36987665, 2023). "This study is dedicated to delve into the impact of the relationship between temozolomide and the LINC00470/EGR2/SOX4 axis on glioblastoma progression, thus presenting a fresh theoretical basis for the treatment of glioblastoma with temozolomide." (PMID 36987665, 2023). "Although depending on the type of cancer SOX4 can act as a tumor suppressor or an oncogene, it has been shown to limit glioblastoma cell proliferation." (PMID 35721477, 2022). "CRISPR/Cas9-mediated knockdown of tRNAiMet inhibits glioblastoma cell proliferation and the replenishing of ectopic tRNAiMet partly rescues the Sox4-mediated proliferation inhibition." (PMID 34073089, 2021).
glioblastoma (continued). "miR-29a downregulates PTEN, EphB3 and SOX4 expression to activate a complex post-transcriptional program of growth and invasion in glioblastoma." (PMID 30683134, 2019). "Western blot analysis revealed upregulation of HIC5 protein expression after exposure of human U251 glioblastoma cells to the miR-29a mimic or after siRNA-mediated knockdown of Sox4." (PMID 30683134, 2019). "This pattern suggests that the miR-29a/Sox4/HIC5 invasion pathway is functional in glioblastomas in vivo." (PMID 30683134, 2019). "Computational analysis of microRNA and mRNA expression profiles from 261 primary glioblastoma specimens identified Sox4 as the most anti-correlated predicted mRNA target of miR-29a (PCC = − 0.636)." (PMID 30683134, 2019). "Our finding that miR-29a increases growth and invasion by downregulating PTEN, EphB3 and Sox4 in glioblastoma indicates the presence of a coordinated program promoting tumor aggressiveness." (PMID 30683134, 2019). "The results showed that NGN2 and SOX4/11 could reprogram primary glioblastoma cell lines (GBM) into neuron‐like cells with approximately 95% efficiency, as measured by the ratio of cells expressing TUJ1 and MAP2." (PMID 39390804, 2024). "Taken together, temozolomide may restrain the malignant behaviors of glioblastoma by dampening the LINC00470/EGR2/SOX4 axis." (PMID 36987665, 2023). "Overall, temozolomide treatment might block the LINC00470/EGR2/SOX4 axis to constrain glioblastoma growth in vivo." (PMID 36987665, 2023). "This study further ascertained whether the regulation of temozolomide on cell apoptosis and autophagy in glioblastoma also involved the LINC00470/EGR2/SOX4 axis." (PMID 36987665, 2023). "Temozolomide repressed glioblastoma progression by repressing the LINC00470/EGR2/SOX4 axis." (PMID 36987665, 2023). "Collectively, temozolomide might repress cell proliferation, migration, invasion, and angiogenesis in glioblastoma through the disruption of the LINC00470/EGR2/SOX4 axis." (PMID 36987665, 2023). "SOX4 in Glioblastoma sustains stemness and is regulated by TGF-β." (PMID 35538578, 2022). "Sox4 can target all copies of an individual tRNA isodecoder gene in human glioblastoma cells, e.g., 8 genomic copies of tRNAiMet (located in Chromosome (Chr) 1, Chr 6, and Chr 17) and 6 genomic copies of tRNAPhe (located in Chr 6, Chr 11, Chr 12, Chr 13, and Chr 19)." (PMID 34073089, 2021). "In addition to the AKT/PI3 kinase and Wnt pathways, miR-29a activates a newly-discovered Sox4/Hic5 invasion pathway in glioblastoma cells." (PMID 30683134, 2019). "However, we did observe robust upregulation of HIC5 after miR-29a exposure or Sox4 knockdown in glioblastoma cells." (PMID 30683134, 2019). "Western blot analysis indicated that miR-29a robustly downregulates Sox4 protein expression in multiple human glioblastoma cell lines and in primary glioblastoma stem-like cells, and the miR-29a inhibitor (100 nM) increased Sox4 protein levels in primary glioblastoma stem-like cells." (PMID 30683134, 2019). "Overexpression of SOX4 has been reported in many cancers including glioblastoma multiforme (GBM), however, the underlying mechanism of actions has not been studied." (PMID 25366337, 2014). "Therefore, we hypothesized that temozolomide may delay the development of glioblastoma by inhibiting the transcriptional activation of SOX4 through LINC00470‐regulated EGR2." (PMID 36987665, 2023). "SOX4 and Mcam are upregulated in glioblastoma vessels and could promote tumor angiogenesis." (PMID 34867089, 2021). "Indeed, we identified Sox4 as the most anti-correlated predicted target of miR-29a in glioblastoma." (PMID 30683134, 2019). "In human glioblastoma, IL-6 levels are endogenously lower in patients who achieve histological or radiographic responses to ICI, and ICI-resistant glioblastoma has elevated stem cell markers (SOX2, SOX4, SOX13, PTPRZ1), which can be driven by IL-621,58." (PMID 40161763, 2025).
glioblastoma (continued). "Temozolomide restrained glioblastoma growth and angiogenesis in vivo, while LINC00470 or SOX4 overexpression nullified but LINC00470 knockdown further facilitated these trends." (PMID 36987665, 2023). "This study illustrated that temozolomide suppressed cell proliferation, migration, invasion, and angiogenesis, but accelerated cell apoptosis, autophagy in glioblastoma, as well as restricted tumor growth in vivo, by disrupting the LINC00470/EGR2/SOX4 axis." (PMID 36987665, 2023). "Sox4 is the most anti-correlated predicted target of miR-29a in glioblastoma and is positively correlated with survival, while HIC5 expression is upregulated by miR-29a or by decreased Sox4, and is anti-correlated with survival." (PMID 30683134, 2019). "Overexpression of the miR-29a sponge increased Sox4 protein expression and decreased HIC5 protein expression in U251 glioblastoma cells." (PMID 30683134, 2019). "We depleted endogenous Sox4 protein expression via transient transfection of Sox4 siRNA in LN229 or U251 glioblastoma cells, and found that this significantly increased glioblastoma cell invasion (P < 0.0001, unpaired t-test)." (PMID 30683134, 2019). "In our study, human SOX4 and SOX11 either could highly efficient (95%) reprogramming U251 cell into neuron cell, which is a promising strategy for glioblastoma therapy." (PMID 39390804, 2024). "Altogether, temozolomide treatment might also facilitate apoptosis and autophagy of glioblastoma cells in vivo and in vitro by blocking the LINC00470/EGR2/SOX4 axis." (PMID 36987665, 2023). "It was discovered in a prior work that the ALK pathway includes the SOX4, Sta3, Akt, and N‐myc activities, which jointly facilitated cell proliferation and tumor neovascularization in nonhypoxic contexts in glioblastoma." (PMID 36987665, 2023). "Temozolomide treatment induced cell cycle arrest, diminished cell viability, migration, invasion, and angiogenesis, and increased apoptosis and autophagy in glioblastoma, which was counteracted by overexpressing LINC00470 or SOX4 but was further promoted by LINC00470 knockdown." (PMID 36987665, 2023). "Accumulated evidence indicates that several SOX members have been identified as tumor-specific antigens that can augment cytotoxic T lymphocytes (CTLs) response to kill cancer cells, including SOX2 (glioblastoma), SOX4 (lung cancer), SOX6 (glioblastoma), and SOX11 (glioblastoma)." (PMID 35267473, 2022). "Taken together, these data indicate that miR-29a targets Sox4 to promote glioblastoma cell invasion independent of PTEN." (PMID 30683134, 2019). "Another relevant example is TGFBI which, besides its recognized role as a marker of the mesenchymal class of glioblastoma, was described, in conjunction with SOX4, as a mediator of non-SMAD mediated TGF-beta signaling pathways in glioblastoma." (PMID 26188123, 2015). "In addition, a study has shown that miR-29a increases growth and invasion in glioblastoma; this program involves not only coactivation of the AKT/PI3K and Wnt pathways through the downregulation of PTEN and EphB3, but also the activation of a newly discovered Sox4/Hic5 invasion pathway." (PMID 33014873, 2020).
liver cancer (30 papers, 2010 to 2025). An epithelial or non-epithelial malignant neoplasm that arises from the liver. "Upregulated pathways were associated with MYC targets, cellcycle, liver cancer, dividing cells, methylation, SOX4 targets, IL6deprivation, senescence and tumor microenvironment." (PMID 40821580, 2025). "The Mas and Wurmbch liver cancer datasets have reported that SOX4 is highly expressed in hepatitis C virus-associated HCC 26, 27, which is consistent with our results." (PMID 33995626, 2021). "ALKBH5 amplifies the characteristics of liver cancer stem cells by mediating the expression of SOX4 and activating the SHH signaling pathway, thereby conferring resistance to radiotherapy." (PMID 40823093, 2025). "The regulation of SOX4 significantly altered the expression levels of triglycerides in liver cancer cells and cholesterol." (PMID 40399256, 2025). "HAGLR also plays a role in the miR-130a-3p/SOX4 (SRY-box 4) axis in liver cancer and in the miR-608/FZD4 (frizzled class receptor 4) axis in ovarian cancer." (PMID 37624034, 2023). "The lncRNA HOXD-AS1 is reported to facilitate metastasis of liver cancer by competitively bound to miR-130a-3p that prevented SOX4 from miRNA-mediated degradation." (PMID 35013132, 2022). "Studies have found that overexpression of SOX4 regulates the CXCL12 promoter in liver cancer cells to enhance tumor-induced angiogenesis, which contributes to distant tumor metastasis and causes poor prognosis in liver cancer patients." (PMID 35573654, 2022). "A positive correlation between SP1 and SOX4 was observed through TCGA liver cancer data (n = 361, p = 4.9e−23, R = 0.46)." (PMID 35924788, 2022). "Previously, an oncogenic role for SOX4 was identified in liver cancer, acute myeloid leukemia, and pancreatic cancer." (PMID 34429400, 2021). "The STAT3-mediated lncRNA HOXD-AS1 is upregulated by ceRNA and subsequently promotes the metastasis of liver cancer by regulating SOX4." (PMID 34101736, 2021). "LncSox4, which physically binds to STAT3 and recruits a transcription factor to the SOX4 promoter, leads to SOX4 transcription and liver cancer cell self-renewal." (PMID 32669100, 2020). "For instance, lncRNA HOXD-AS1 promotes liver cancer metastasis through sponging miR-130a-3p and targeting SOX4." (PMID 32795273, 2020). "For example, STAT3-induced lncRNA HOXD-AS1 facilitates liver cancer metastasis by competitively sponging miR-130a-3p and regulating SOX4." (PMID 32351327, 2020). "Sox4 expression levels are also related to liver cancer progression and prognosis, providing a new potential marker for HCC diagnosis and prognosis." (PMID 27553854, 2016). "Sox4-deficient cells formed smaller tumours compared with WT cells, indicating the essential role of Sox4 in liver cancer propagation." (PMID 27553854, 2016). "We detected Sox4 expression levels using real-time PCR, western blot and immunohistochemistry (IHC), and confirmed high Sox4 expression in liver cancer, especially in advanced HCC tissues." (PMID 27553854, 2016). "Amongst other over expressed miRNAs, miR199b has transcription factors like SOX4 and has been shown to be involved in liver cancer and muscular dystrophy." (PMID 20158877, 2010). "Reminiscent of human liver cancers that express both lineages, we noted the upregulated expression of stemness markers such as Sox9, Sox4, Cd44, Prom1 and Cd24a in HepYF-M13 and HepYF-M14 cells compared to their expression in normal hepatocytes and H2.35 immortalized hepatocytes." (PMID 39051113, 2024). "Besides its role in stemness maintenance and development regulation, we uncovered the critical role of Sox4 in liver cancer initiation, progress and prognosis prediction." (PMID 27553854, 2016). "In addition, we could observe positive correlations of the expression levels of GOLGB1 or SF3B3 with the expression levels of CXCL8 and SOX4 in the liver cancer data of TCGA, implying the potential connection between them." (PMID 28038442, 2017).
liver cancer (continued). "We further verified the increased expression of Sox4, E2f1, Trpv4, and Trim6 in DEN-induced, Srsf3 KO liver cancer tissues by qRT-PCR." (PMID 40568073, 2025). "Overexpression of HOXD-AS1 competitively binds miR-130a-3p and prevents SOX4 miRNA-mediated degradation, thereby activating the expression of EZH2 and MMP2, and promoting liver cancer metastasis." (PMID 35706002, 2022). "There was a positive correlation between BMI1/SOX4 and YAP in liver cancer patients (R = 0.56, P < 0.05, R = 0.5, P < 0.05)." (PMID 35322024, 2022). "On the other hand, SOX4 has been shown to promote HBV replication by stimulating viral DNA replication and protein expression in liver cancer cells." (PMID 33995626, 2021). "In this article, the authors show that a previously unidentified lncRNA, LncSox4, is highly expressed in liver cancer TICs and regulates TIC self-renewal through the Stat3/SOX4 axis." (PMID 27553854, 2016). "Moreover, the up-regulation of some genes related to the stemness of cancer cells, such as EpCAM, CD133, CD44, Oct4, Nanog, KLF4 and Sox4, in USP16-depleted liver cancer cells also suggests a stemness-suppressing role for USP16." (PMID 27633997, 2016). "The relationship between Sox4 and TIC surface markers were analysed using Wang's cohort (GSE14520 (refs 31, 32), with gene microarray data and survival information of two normal liver samples, 228 peri-tumour and 239 liver cancer samples) and Li's cohort (GSE40144)." (PMID 27553854, 2016).